TRPV1 (transient receptor potential cation channel subfamily V member 1)
Diseases named in the same sentence as TRPV1 in open-access papers (continued):
Sharing a sentence is not in itself a finding about the gene and the disease.
bone cancer (continued). "PD-L1/PD-1 signaling suppresses TRPV1 activity and alleviates pain-like behaviors via phosphorylation of SHP-1 in nociceptive primary sensory neurons in a mouse bone cancer model." (PMID 32960817, 2020). "The dose-response curve of TRPV1 currents was left-shifted on PTD 21, suggesting the sensitization of TRPV1 in bone cancer mice." (PMID 32960817, 2020). "Here, we show that PD-L1 activated Src homology 2 domain-containing tyrosine phosphatase-1 (SHP-1) to downregulate transient receptor potential vanilloid 1 (TRPV1) in DRG neurons and inhibit bone cancer pain in mice." (PMID 32960817, 2020). "Previous studies revealed that following tumor infiltration TRPV1 expression increases in the DRG and contributes to bone cancer pain both in mice and in rats." (PMID 32960817, 2020). "It was found that TRPV1 protein level and TRPV1-positive neurons increased in DRG from a murine model of bone cancer, while treatment with a receptor antagonist significantly attenuated painful symptoms." (PMID 24288041, 2011). "The findings that co-localization of TRPV1 and LPA1 receptor EDG-2 and bone cancer induced an increase in LPA1 receptor expression in DRG provide further support for these phenomena." (PMID 21118579, 2010). "Given that bone cancer pain characterizes neuropathic pain, it is conceivable that LPA-induced potentiation of TRPV1 current reflects an increase in excitability of uninjured fibers innervating the adjacent region of osteocarcinoma." (PMID 21118579, 2010). "TRP vanilloid 1 (TRPV1) and ankyrin 1 (TRPA1) abundantly expressed on capsaicin-sensitive peptidergic sensory fibers have been suggested to be involved in chronic tumoral pain, including bone cancer." (PMID 38791867, 2024). "Many other inhibited TRPV1 compounds, such as JNJ-17203212, JNJ-39439335, and JNJ-38893777, have been found to be effective in various pain models, and some, such as SB366791, demonstrate potential analgesic effects in bone cancer pain." (PMID 37664239, 2023). "There was a report indicated that HMGB1 contributed to bone cancer pain by upregulation of TRPV1, but the behind mechanism had not been fully illustrated." (PMID 36438444, 2022). "Although the antagonist of TRPV1 attenuated the pain behavior, blockade TRPV1 not always reduced bone cancer pain indicating that the regulation of TRPV1 was multiple." (PMID 36438444, 2022). "All the studies suggested that TRPV1 in DRG was upregulated and involved in bone cancer pain." (PMID 36438444, 2022). "Neither PWL nor bone cancer–induced mechanical allodynia was changed by local injection of PD-L1 (5 μg) in tumor-bearing TRPV1–/– mice." (PMID 32960817, 2020). "In the present study, we investigate the role of PD-L1/PD-1 in mouse bone cancer pain by Lewis lung carcinoma (LLC) cell inoculation and address whether PD-L1 modulates TRPV1 in DRG nociceptive neurons from control mice and mice with cancer pain." (PMID 32960817, 2020). "For example, prior studies have reported interaction of TRPV1 with NMDA receptors and with lysophosphatidic acid receptors via a PKC-mediated mechanism to mediate peripheral mechanical hypersensitivity in the context of muscle pain and bone cancer pain." (PMID 29497363, 2018). "TRPV1-dependent thermal hyperalgesia is present in animal models of SCC and bone cancer." (PMID 24524628, 2014). "Interestingly, over-expression of TRPV1 has been found in bone morrow, DRG neurons and afferent C-fibers in bone cancer pain models." (PMID 20422007, 2010). "Capsaicin could evoke a TRPV1 current (the lower trace) in 8 out of 12 neurons after perfusion of LPA (0.01 μM), indicating LPA-induced potentiation of TRPV1 currents under bone cancer state." (PMID 21118579, 2010). "It has to be kept in mind that the mechanisms by which cancer activates TRPV1 are unknown, therefore it is not clear either whether cancer models mimic human bone cancer pain." (PMID 38339399, 2024).
bone cancer (continued). "Besides, PD-L1-induced analgesia on bone cancer pain was only observed in wild-type but not in TRPV1-KO mice." (PMID 36438444, 2022). "In bone cancer pain, the acidic microenvironment could activate the TRPV1 channel although the expression of TRPV1 mRNA had no change." (PMID 36438444, 2022). "PD-L1–induced analgesia on bone cancer pain only occurred in WT but not in TRPV1-KO mice." (PMID 32960817, 2020). "In a rat bone cancer model using Walker 256 mammary gland carcinoma cells, we observed that TRPV1 expression level and capsaicin-induced TRPV1 currents are increased in ipsilateral DRG neurons with tumor inoculation in bone, and blockade of TRPV1 reduces bone cancer pain." (PMID 32960817, 2020). "It was found that TRPV1 is upregulated in post-herpetic neuralgia, bone cancer and in inflammation in which the channel might even be expressed in sensory neurons that do not usually express TRPV1." (PMID 30813430, 2019). "When intrathecally administrated, a powerful TRPV1 agonist resiniferatoxin (RTX, a component contained in the dried latex of the cactus-like plant;) produced a prolonged antinociceptive response in dogs with bone cancer, possibly owing to a desensitization of TRPV1 channel." (PMID 27483289, 2016). "In addition to TRPV1, LPA could modulate other targets in the induction of bone cancer pain, which might be mediated by Rho pathway." (PMID 21118579, 2010). "A very low concentration of capsaicin (0.5 nM) failed to evoke TRPV1 currents in all of the DRG neurons tested (n = 11) in sham-operated rats, whereas 40% of the DRG neurons tested (n = 20) were responsive to capsaicin in bone cancer rats." (PMID 21118579, 2010).
Arthritis (49 papers, 2009 to 2026). Inflammation of a joint. "HMC treatment reduced the basal neuronal activation caused by TiO2-induced arthritis as well as the responsiveness of TRPV1+ and TRPA1+ DRG neurons, which are two important subsets of nociceptive neurons." (PMID 36677929, 2023). "Nerve growth factor (NGF) is an important inflammatory mediator implicated in arthritis that binds to its high affinity receptor tropomyosin receptor kinase A (TrkA) and can increase TRPV1 expression." (PMID 30240782, 2018). "Genetic data also implicates TRPV1 as a major player in arthritis pain, as the Ile585Val genetic variant within the coding region of the TRPV1 gene is correlated with reduced symptomatic pain complaints in patients suffering from OA." (PMID 30326593, 2018). "We believe that one of the mechanisms underlying the attenuation of arthritis development by SA13353 is inhibition of TNF-a production by inflammatory cells exposed to neuropeptides released from TRPV1-expressing afferent C fibers." (PMID 24280677, 2012). "Therefore, it is essential to identify sex‐specific genes related to TRPV1 and elucidate the underlying mechanisms of gender differences in the treatment of arthritis pain." (PMID 37994506, 2024). "Thus, DRG TRPV1+ neurons are likely more susceptible to LXA4 action during TiO2 arthritis than when uninflamed, supporting the analgesic effect of LXA4." (PMID 37388729, 2023). "Additionally, CFA induced arthritis causes a significant increase in TRPV1 expression on the overall proportion of unmyelinated nerves innervating the paw and on DRG neurons." (PMID 33193423, 2020). "ASIC3 or TRPV1 deficiency attenuated arthritis-associated hyperalgesia in the chronic phase (after 6 or 8 weeks) and TDAG8 knockout attenuated the hyperalgesia in the acute and chronic phases, but TDAG8 knockdown only attenuated acute phase (before 4 weeks) of RA pain." (PMID 28827659, 2017). "Similar experiments of TRPV1-deficient mice explored the role of TRPV1 in arthritis." (PMID 28827659, 2017). "Increased TRPV1 expression in synovial fibroblasts of arthritis patients correlates with higher cytokine production." (PMID 41569118, 2026). "Study showed that TRPV1 knockout mice showed reduced arthritis progression after adjuvant treatment." (PMID 41569118, 2026). "We have discussed the expression and functional correlation of TRPV1 in different tissues under arthritis condition, as well as the role of TRPV1 in arthritis pain." (PMID 37994506, 2024). "TRPV1 not only serves as a source of anti‐ferroptosis in chondrocytes but also is imperative for inflammation and pain progression in arthritis." (PMID 37994506, 2024). "In rats with complete Freund's adjuvant‐induced arthritis, intrathecal injection of a Nogo‐A receptor antagonist has been shown to reduce the TRPV1 content in the DRG and effectively relieve chronic pain." (PMID 39622788, 2024). "The expression of TRPV1 mRNA and protein in synovial tissue is increased in human and rat arthritis models." (PMID 37994506, 2024). "First, the contribution of TRPV1 to angiogenesis and lymphangiogenesis in arthritis pathogenesis should be assessed." (PMID 37994506, 2024). "TRPV1 antagonists and activators serve as agents that contribute to the analgesic effects in arthritis." (PMID 37994506, 2024). "The TRPV1 channels play a crucial role in nociception during arthritis, and numerous studies have observed an upregulation of this channel on sensory nerves in relation to arthritis pain." (PMID 37994506, 2024). "In summary, the involvement of TRPV1 in the development of arthritis highlights its significance in the disease's pathogenesis." (PMID 37994506, 2024). "While several TRPV1 agonists or antagonists have demonstrated improved efficacy in pre‐clinical and clinical trials for arthritis pain, attention needs to be given to adverse reactions, such as drug‐induced increases in core body temperature." (PMID 37994506, 2024).
Arthritis (continued). "Extensive evidence in recent years has established the significant involvement of TRPV1 in the development of arthritis pain and inflammation, positioning it as a promising therapeutic target for arthritis." (PMID 37994506, 2024). "When arthritis occurs, HA elastoviscous filtering capacity decreases, reducing the regulation of the TRPV1 channel and increasing the excitability of peripheral nociceptive neurons." (PMID 37994506, 2024). "In MIA‐induced arthritis rats, PKCɛ activates TRPV1 by inducing TRPV1 phosphorylation at Ser800, resulting in inflammatory hyperalgesia in the rats." (PMID 37994506, 2024). "TRPV1 channels are widely expressed in histiocytes, nerves and brain regions that are relevant to arthritis pathophysiology." (PMID 37994506, 2024). "Most current studies on the role and mechanisms of TRPV1 channels in arthritis pain have primarily involved male rodents." (PMID 37994506, 2024). "It is possible to alleviate arthritis pain by inhibiting angiogenesis and lymphangiogenesis through the inhibition of TRPV1 activity." (PMID 37994506, 2024). "In order to make better use of TRPV1 channels for the treatment of arthritis, the following problems need to be addressed." (PMID 37994506, 2024). "We summarize and analyse current studies regarding the biological functions and mechanisms of TRPV1 in arthritis." (PMID 37994506, 2024). "Anticipated future studies will shed more light on the precise role and regulatory mechanisms of TRPV1 in arthritis." (PMID 37994506, 2024). "In a rat model of arthritis, specific activation of TRPV1+ neurons by capsaicin injection inhibits M1 polarization in the synovial membrane via the Ca2 + /CaMKII/Nrf2 signaling pathway, thereby delaying the progression of osteoarthritis." (PMID 38129779, 2023). "It is interesting that TiO2-induced arthritis also enhanced the response to capsaicin, a TRPV1 agonist; thus, TiO2-induced arthritis enhances the activation of TRPV1+ nociceptive neurons." (PMID 36677929, 2023). "Altogether, these results suggest that nociceptive TRPV1+ neurons are targets of the action of LXA4 during TiO2-induced arthritis." (PMID 37388729, 2023). "In joint inflammation, the synovial compartments can also be exposed to thermal (>43°C), chemical, and osmotic modifications which can activate the TRPV1 membrane sensors which respond by activating calcium and sodium fluxes." (PMID 36937015, 2023). "Genetic ablation of TRPV1 in mice reduced pain in an adjuvant-induced arthritis model and IP injection of the TRPV1 antagonists, A-889425 and JNJ-17203212, reduced pain behaviors in the monoiodoacetate-induced OA model." (PMID 37259103, 2023). "We observed that ALX/FPR2 receptor staining was increased in TiO2-induced arthritis, and more specifically, TRPV1+ nociceptive neurons express ALX/FPR2 receptor and that TiO2 inflammation enhances the percentage of ALXR+/TRPV1+ neurons." (PMID 37388729, 2023). "Polypeptide APHC3, a mode-selective TRPV1 antagonist, can significantly reverse mechanical hypersensitivity in the arthritis model." (PMID 34471470, 2021). "TRPV1 is greatly involved in thermal hypersensitivity generated by inflammation including arthritis-induced thermal hypersensitivity." (PMID 33477357, 2021). "The attenuation of pain behavior in arthritis animals models has been demonstrated for a variety of TRPV1 antagonists, such as JNJ-17203212, SB366791, and some others." (PMID 33477357, 2021). "Further, swelling of the knee joint and thermal hyperalgesia in TRPV1 knockout (KO) mice were reported to be reduced in CFA-induced arthritis." (PMID 34681836, 2021). "In the present work, we investigated the analgesic and anti-inflammatory effects of APHC3, a polypeptide modulator of TRPV1 channel, in two rat models of arthritis." (PMID 33477357, 2021). "Inhibition of TRPV1 reduces arthritis severity and depletes neuropeptide levels induced by increased intracellular calcium." (PMID 34681836, 2021).
Arthritis (continued). "The role of TRPV1 in nociception and joint inflammation in arthritis has been proven by a number of investigations." (PMID 33477357, 2021). "In a preclinical model of rheumatoid arthritis, depletion of TRPV1 positive cells reduced arthritis severity and depleted neuropeptide levels resulting from increased intracellular calcium." (PMID 34681836, 2021). "In arthritis, inhibition of TRPV1 has identified it as a potential target for therapeutic interventions." (PMID 33193423, 2020). "In the complete Freund’s adjuvant (CFA) pre-clinical model of arthritis, capsaicin depletion of TRPV1-positive cells, reduces arthritis severity and depletes neuropeptide levels." (PMID 33193423, 2020). "In a mono-iodo-acetate-induced (MIA) arthritis model in rats, 71% of sensory neurons stained positive for TRPV1 when using immunohistochemistry, compared to 54.3% of sensory neurons in control rats injected with saline." (PMID 32197454, 2020). "Topical application of capsaicin, the active ingredient in chili peppers, has proven to be beneficial in treating arthritis and diabetic peripheral neuropathy, possibly by the desensitization of TRPV1 channels." (PMID 33105614, 2020). "Administration with SST analogs or TRPV1 agonists can alleviate synovial thickening, cell infiltration, cartilage destruction, and bone erosion in rats with artificial arthritis." (PMID 31189399, 2019). "During gout arthritis there is an increase of TRPV1-dependent activation of primary nociceptor sensory neurons." (PMID 30914954, 2019). "In particular, administration of a TRPV1 agonist inhibits TNF production in a rat model of arthritis." (PMID 30761069, 2019). "Both preclinical and clinical data strongly support a role for various TRP channels, especially TRPA1 and TRPV1, in arthritis pain and pathogenesis." (PMID 30326593, 2018). "While TRPV1 has been more frequently studied in relation to arthritis pathogenesis, there is ample evidence of a role for TRPA1 in models of OA, RA, and gout as well." (PMID 30326593, 2018). "Although the TRPA1 and TRPV1 channels have received the greatest attention for their role in arthritis-related models, several other TRP channels have also been studied in this context." (PMID 30326593, 2018). "TRPV1−/− animals display reduced pain following Complete Freund’s Adjuvant (CFA)-mediated arthritis induction compared to TRPV1+/+ animals as judged by weight-bearing ratio between the affected and unaffected legs." (PMID 30326593, 2018). "Mean arthritis scores increased in TRPV1−/− mice over time, but the severity of arthritis was largely reduced from week 2 as compared with TRPV1+/+ mice (p = 0.007 at 2 weeks, p < 0.000001 at 12 weeks)." (PMID 28827659, 2017). "This strongly suggests that TRPV1 channels play a pivotal role in pain mediation, as described in neuropathy and arthritis models, but the time course-dependent involvement of these channels has never been proven." (PMID 25524130, 2015). "The importance of TRPV1 in arthritis is emphasized in knock-out animals that show an attenuated disease." (PMID 26343051, 2015). "TRPV1 also has a crucial function in afferent of experimental arthritis by triggering peripheral neuropeptides release, such as calcitonin-gene related peptide." (PMID 24605047, 2014). "Recent studies have described that TRPV1 activation is essential for the establishment of inflammation and pain in models of arthritis, showing that the expression of this receptor is increased, contributing to enhanced thermal sensitivity." (PMID 24941071, 2014). "We investigated the effects of the TRPV1 agonist SA13353 on the development of arthritis in collagen-induced arthritis in rats." (PMID 24280677, 2012). "In contrast, TRP channel function and regulation in non-neuronal cells such as synovial fibroblasts are less well studied, although the physiologic contribution of TRPV1 in experimental arthritis has been well documented recently using TRPV1-knockout mice." (PMID 19695100, 2009).